AR (androgen receptor)
Diseases named in the same sentence as AR in open-access papers (continued):
Sharing a sentence is not in itself a finding about the gene and the disease.
prostate carcinoma (continued). "In prostate cancer, loss of the repressive function of NCOR2 altered the AR response to ligands and contributed to cancer development." (PMID 37131060, 2023). "We also found FEN1 expression was positively correlated with AR expression in prostate cancer (r = 0.3, p < 0.001)." (PMID 37326412, 2023). "The target androgen responsive genes cannot be activated, and prostate cancer growth cannot be stopped if the androgen receptor is somehow kept in the cytoplasm and its shuttling into the nucleus is blocked." (PMID 38027169, 2023). "While MBOAT2 was upregulated in prostate cancer cells upon androgen receptor (AR) activation, MBOAT1 is regulated downstream of the estrogen receptor alpha (ERα) in breast cancer cells." (PMID 37679313, 2023). "The androgen receptor (AR) signaling pathway plays a significant role in the progression of prostate cancer by facilitating the process of autophagy." (PMID 37834333, 2023). "In the past 30 years, huge number of anti-AR drugs have been developed and approved for different stages of prostate cancer, such as flutamide, bicalutamide, nilumet, and enzalutamide." (PMID 36744249, 2023). "The results of these cell cycle experiments demonstrate that S‐phase arrest in prostate cancer cells induced by DTX was enhanced by AR knockdown." (PMID 37326412, 2023). "Androgen receptor signaling is the major stimulus for prostate cancer initiation and progression to CRPC." (PMID 38001678, 2023). "The three major non-receptor tyrosine kinases, FAK, SRC and ETK, form the SRC tyrosine kinase complex, which in prostate cancer is suggested to play an important role in the aberrant activation of the androgen receptor (AR) by phosphorylation." (PMID 36673031, 2023). "After analyzing a prostate cancer tissue microarray patient cohort, CD151-associated integrin α3β1 and integrin α6β4 exhibited an inverse correlation with AR expression." (PMID 37681860, 2023). "In prostate cancer, the modulation of the androgen receptor plays a pivotal role in driving the progression of the disease to a castration-resistant state." (PMID 38067315, 2023). "Our research confirms a new mechanism of AR blocking in the treatment of prostate cancer and offers FEN1 as a promising anticancer therapeutic target for prostate cancer treatment in order to overcome DTX resistance." (PMID 37326412, 2023). "METTL23 has been validated as a prognostic marker in prostate cancer, and the coactivation properties of WDR77 on the androgen receptor have been linked to ovarian cancer." (PMID 38132437, 2023). "Drugs like enzalutamide, apalutamide, and darolutamide effectively inhibit AR signaling, demonstrating efficacy in castration-resistant prostate cancer." (PMID 37686423, 2023). "To begin studying our drug combinations, we selected prostate cancer cell lines with different AR genetic backgrounds that also express SRC kinase, expecting a myriad of responses that will allow us to evaluate synergy between our selected drugs." (PMID 37456235, 2023). "Prostate transmembrane androgen inducible protein 1 (PMEPA1) can promote or inhibit prostate cancer cell growth based on the cancer cell response to the androgen receptor (AR)." (PMID 38173834, 2023). "The FKBP52 cochaperone is a positive regulator of androgen (AR), glucocorticoid (GR), and progesterone receptor (PR) function and represents an attractive target for the treatment of castration-resistant prostate cancer." (PMID 36602710, 2023). "With only few exceptions, compounds that potently inhibited colony formation of ER+ cells also potently inhibited the clonal expansion of the AR+ prostate cancer cell lines." (PMID 37520743, 2023). "In our present study, we aimed to investigate the effect of Lova alone and the combination Duta + Lova on cell viability as well as PSMA and AR expression in three established prostate cancer cell lines (LNCaP, C4-2 and VCaP)." (PMID 37569712, 2023).
prostate carcinoma (continued). "Over the last two decades, genetic and epigenetic alterations have been identified as oncogenic drivers to modulate AR-dependent cistrome reprogramming during prostate cancer development, progression, and treatment resistance." (PMID 36776320, 2023). "While the androgen receptor is the familiar target for PCa detection and therapy, more estrogens and their receptors have been involved in developing prostatic carcinoma." (PMID 36834602, 2023). "To investigate the phosphorylation status of AR and MED1 as a consequence of methyl-PP2A-C loss and the resultant bias in PP2A heterotrimer formation upon LCMT1 silencing, we employed a panel of prostate cancer cell lines stably expressing shRNA to LCMT1." (PMID 37644036, 2023). "MYB acts as a potentiator of aggressiveness and castration resistance in prostate cancer (PCa) through aberrant activation of androgen receptor (AR) signaling." (PMID 38089573, 2023). "Prostate cancer (PCa) development and progression relies on the programming of glucose and lipid metabolism, and this involves alterations in androgen receptor expression and signalling." (PMID 37596305, 2023). "The vast majority of prostate cancers are adenocarcinomas of a luminal phenotype that express the transcription factor androgen receptor (AR) and are highly dependent on AR signaling." (PMID 37183816, 2023). "Even though both LNCaP and 22Rv1 are AR-positive prostate cancer cell lines, they bear one critical difference." (PMID 37111288, 2023). "Dysregulated expression of AR co-regulators contributes to onset and progression of prostate cancer and other types of hormone-dependent cancers, such as bladder, liver, and kidney cancers." (PMID 36746939, 2023). "In summary, this study further elucidated the cross-talk between PKA, HSP90 and AR in prostate cancer." (PMID 37830741, 2023). "It has been reported that elevated intra-tumor androgen levels and high transcriptional activity of the AR signaling pathway are important factors in promoting prostate cancer progression." (PMID 36794010, 2023). "AZD5363, an inhibitor of all isoforms of Akt, has been reported to inhibit proliferation and induce apoptosis in prostate cancer cell lines expressing AR and has antitumor activity in vivo in androgen-sensitive LNCaP xenograft models resistant to castration." (PMID 36768370, 2023). "At the same time, compound 1 resensitized prostate cancer 22Rv1 cells to androgen receptor (AR) blocker enzalutamide." (PMID 36662227, 2023). "The growth of prostate cancer cells is driven by the hyper-activated transcription factor, androgen receptor (AR)." (PMID 36401094, 2023). "For example, ARV-110 is the first oral bioavailable PROTAC small molecule drug that enters clinical trials in the field of PROTAC in world, which can selectively target degradation androgen receptor (AR) to treat prostate cancer." (PMID 37077823, 2023). "Collectively, these data suggest that auraptene suppresses prostate cancer proliferation and AR activity by inducing AMPK activation, which is mediated by an increase in the cellular ADP/ATP ratio and subsequent phosphorylation by LKB1." (PMID 37958994, 2023). "The results of this study show that calcium activates AR and increases cell growth and that calcium channels are overexpressed in hormone-responsive and hormone-resistant prostate cancer cells." (PMID 38131032, 2023). "All ITT patients had received ≥1 prior therapy for prostate cancer, and all patients had received a prior next-generation AR inhibitor." (PMID 36994854, 2023). "AR plays an important role in the tumorigenesis, progression and metastasis of prostate cancer, and is an important target for prostate cancer treatment." (PMID 37326412, 2023). "Aberrant androgen receptor (AR) signaling drives prostate cancer (PC), and it is a key therapeutic target." (PMID 37751307, 2023).
prostate carcinoma (continued). "PROTAC-mediated degradation of the AR and AR variants ((ARV-110, ARV-471, and ARV-766) is currently being investigated in prostate cancer clinical trials." (PMID 36732329, 2023). "Emerging lines of evidence suggest a crucial role of downstream and convergent cellular pathways such as autophagy in AR-driven prostate cancer biology." (PMID 37874216, 2023). "DIM was the first pure androgen receptor antagonist isolated from the Brassicaceae family and has been recently investigated for its potential pharmacological use in prostate cancer prevention and treatment." (PMID 36835033, 2023). "Here, the authors characterise AR genomic complexity across spatially separated lethal metastases from 10 prostate cancer patients and investigate how AR alterations evolve." (PMID 37563129, 2023). "We analyzed the public sequencing data of prostate cancer patients, finding a significant up-regulation of NK1R expression level in treatment-induced NEPC tumors, which was associated with low AR activity, high NE differentiation, and poor prognosis." (PMID 37385990, 2023). "Baicalein inhibited the growth of prostate cancer cells by downregulating the androgen receptor (AR) through AR-N-C dimerization and AR-coactivator interaction." (PMID 37046789, 2023). "Prostate cancer progression is dependent on androgen signaling though the AR, and consequently the first-line treatment strategy for locally advanced or metastatic disease is androgen-deprivation therapy (ADT)." (PMID 37529692, 2023). "It has been shown that in prostate cancer, P300 is able to bind to the androgen receptor (AR) and acetylate it for modification, ultimately leading to enhanced transcription of AR downstream target genes." (PMID 37599359, 2023). "Acquired drug resistance in prostate cancer changes the cell phenotype, and AR-independent pathways are adopted for growth and survival." (PMID 37282627, 2023). "This is consistent with previous results indicating role of both RAS activity and PP2A inhibition in promoting malignant growth of AR-positive prostate cancers." (PMID 36858798, 2023). "Dehydroabietylamine, abietic acid, dehydroabietic acid, and their derivatives 8–24 were purified or synthesized for evaluation on both AR-positive and AR-null prostate cancer cell models since they have a similar core structure as QW07." (PMID 37375297, 2023). "During the early stages of prostate cancer, tumour growth requires the androgenic steroids and the androgen receptor (AR)." (PMID 37363926, 2023). "At the same time, we also found that TAX reduced AR expression in LNCaP and C4-2B cells, while AR signaling is crucial for the proliferation of androgen-dependent prostate cancer cell." (PMID 37567936, 2023). "PARP7 expression levels can be regulated in prostate cancer cells using ligands for AR and AHR, including the NEPC line NCI-H660." (PMID 37077937, 2023). "Since multiple Jumonji domain-containing proteins were reported to modulate AR activity in prostate cancers, we analyze the expression profiles of 35 Jumanji domain-containing genes and their association with clinicopathological features in this study." (PMID 36776320, 2023). "Twenty diterpenoids were prepared for the evaluation of their antiproliferative potency on AR-positive prostate cancer cell models (LNCaP and 22Rv1) using AR-negative cell models (PC-3 and DU145) as comparisons." (PMID 37375297, 2023). "Prostate cancer cell growth and survival is dependent on androgens and androgen receptor, allowing their use as a therapeutic target for advanced, metastatic, or recurrent prostate cancer." (PMID 36614243, 2023). "Significant progress with effective prostate cancer therapies has been made by moving from ligand regulation through androgen deprivation therapy (ADT) to direct blockade of the androgen receptor (AR)." (PMID 38201488, 2023). "Androgen receptor signalling have been highly studied in breast cancer and prostate cancer progression." (PMID 37925508, 2023).
prostate carcinoma (continued). "Using various techniques, 146 to 517 genes and 44 proteins regulated by the AR signaling pathway have been detected in human prostate cancer cells." (PMID 37152995, 2023). "AR ADP-ribosylation is induced by androgen in prostate cancer cells because the PARP7 gene is a direct target of AR, and because PARP7 selectively ADP-ribosylates the agonist conformation of AR." (PMID 37077937, 2023). "ERβ1 exerts a tumor-suppressive effect by negatively regulating the expression and activity of AR in prostate cancer." (PMID 37936981, 2023). "Another example of an AR-targeting PROTAC is ARV-110, which is composed of enzalutamide (a non-steroid AR antagonist which is used in the treatment of castration-resistant prostate cancer) linked to a thalidomide derivative." (PMID 36986673, 2023). "In other words, quercetin has a role in preventing or treating prostate cancer by repressing AR expression." (PMID 36926328, 2023). "It was found that CD4+ T cells were able to enhance prostate cancer cell migration and invasion abilities through downregulation of AR in the prostate cancer cells." (PMID 36836690, 2023). "The alternative mechanism not only helps to better understand the clinical efficacy of docetaxel and cabazitaxel for AR-driven CRPC but also provides an avenue to seek better treatments for various forms of prostate cancer." (PMID 37444418, 2023). "PABPC1 can function to regulate the nuclear localization of AR, and knockdown of PABPC1 reduces AR-positive prostate cancer cell proliferation and transactivation of AR target genes." (PMID 37956771, 2023). "AR is the steroid hormone nuclear receptor that drives the majority of prostate cancer; it plays a key role in the development and progression of prostate cancer, especially in its evolution to advanced stages." (PMID 37445854, 2023). "In this article, we focus on the development of various AR and non-AR target degrading PROTACs and their potential to treat prostate cancer, with an emphasis on drug optimization and medicinal chemistry." (PMID 37175108, 2023). "We also observed that ACAA2 was expressed in ARCaP, which is an AR-low, androgen-repressed prostate cancer cell line that exhibits increased metastatic potential to bones." (PMID 37798372, 2023). "Patients with progressive prostate cancer often develop castration-resistant disease primarily due to the reactivation of the androgen receptor signaling pathway." (PMID 38131032, 2023). "On the other hand, AR functions as an oncogene in prostate cancer cells, promoting cell growth and survival." (PMID 37509723, 2023). "Many studies have highlighted that overexpression of AR signaling relies on prostate cancer initiation and development." (PMID 36969009, 2023). "A previous study showed that AR overexpression increased FEN1 protein levels in prostate cancer cells." (PMID 37326412, 2023). "Our results show that CT7001 also inhibits the transcriptional activity of AR, a key transcription factor and oncogenic driver in prostate cancer." (PMID 37076563, 2023). "In prostate cancer, compared to enzalutamide, an anti-androgen receptor agent, DTHIB shows superiority in decreasing cell viability and inhibiting AR signaling and PSA expression." (PMID 37153737, 2023). "As neuronal axis is one of the major axes for the prostate cancer growth and survival (following AR axis), inhibiting such axis can sensitize cancer cells to the therapy." (PMID 38168280, 2023). "The androgen receptor (AR) is the most critical factor regulating prostate cancer occurrence, progression, and metastasis, and most treatment strategies have been developed to manipulate the AR pathway." (PMID 37326412, 2023). "Together, these data suggest that HDAC inhibition rather than PI3K/AKT pathway inhibition associated with fimepinostat therapy is most likely responsible for the observed perturbation of AR and Myc levels in prostate cancer cell lines." (PMID 37823778, 2023).
prostate carcinoma (continued). "DHT stimulates the androgen receptor-mediated transactivation of several genes, involved in prostate cancer cell growth, carrying an androgen response element (ARE) in their promoters." (PMID 37296999, 2023). "Abnormal activation of AR pathway is an important feature of tumorigenesis and progression in prostate cancer." (PMID 36609444, 2023). "Activation and regulation of androgen receptor (AR) signaling and the DNA damage response impact the prostate cancer (PCa) treatment modalities of androgen deprivation therapy (ADT) and radiotherapy." (PMID 36811381, 2023). "Most prostate cancers can be treated by targeting the androgen-receptor pathway and decreasing androgen production or binding to androgen receptors (AR)." (PMID 37021836, 2023). "As expected, AR protein levels showed a statistically significant decrease in prostate cancer cells after AR was knocked down as compared to cells in the control group." (PMID 37326412, 2023). "Enhancer profiling from plasma allowed us to infer activity of therapeutically targetable TFs from plasma, including estrogen receptor (ER) in breast cancer plasma, androgen receptor (AR) in prostate cancer and HIF2α in renal cell carcinoma (RCC)." (PMID 37865722, 2023). "A few studies have reported that the up-regulation of ECI2 which is considered as a downstream target of androgen receptor promotes prostate cancer progression and inhibits cell death response through lipid degradation." (PMID 37535601, 2023). "Because LNCaP cells are AR+ hormone-dependent prostate cancer cells, they were chosen to validate drug sensitivity." (PMID 37904122, 2023). "The androgen receptor (AR) signaling pathway plays a crucial role in the development of prostate cancer." (PMID 37765058, 2023). "Encouraged by the promising data, the present study aims to investigate the relationship between four core structures and their antiproliferative activities towards both AR-positive (LNCaP) and AR-null (PC-3 and DU-145) prostate cancer cell lines." (PMID 37111288, 2023). "We chose TMPRSS2:ERG fusion because this is the most frequent molecular alteration found in prostate cancer, and IHC data on AR expression because of its known interaction with PSAP." (PMID 37892063, 2023). "Newly developed AR targeted therapies, such as enzalutamide and abiraterone, have shown promise as effective treatments for advanced prostate cancer." (PMID 37234978, 2023). "It decreased cellular proliferation and reduced tumor growth in both in vitro and in vivo, potentially making it effective against castration-resistant prostate cancer by degrading both AR-V7 and AR-FL." (PMID 37175108, 2023). "Classically, AR plays a critical role in the development and progression of all stages of prostate cancer and remains a major therapeutic target." (PMID 36831540, 2023). "It has been demonstrated in prostate cancer that the inhibition of PI3K leads to the activation of AR, while the loss of AR activity promotes PI3K/AKT pathway activity." (PMID 38067367, 2023). "In another word, LAT3 is highly expressed in prostate cancer cells that expressed the androgen receptor (AR)." (PMID 37047148, 2023). "Recently, shared androgen receptor (AR) binding has been established between primary EA prostate cancer samples and prostate cancer cell lines, such as LNCaP, supporting cell line research utility." (PMID 37082578, 2023). "PSMA expression on prostate cancer cells is heavily modulated by treatments that alter androgen receptor." (PMID 37493837, 2023). "We treated LNCaP, a human prostate cancer cell line that expresses AR, with enzalutamide or pinostilbene in a concentration-dependent manner." (PMID 37794090, 2023). "The impact of AR blockade on the lipid profiles of prostate cancer patients has furthermore been outlined." (PMID 36768610, 2023).